UMOD (uromodulin)
Diseases named in the same sentence as UMOD in open-access papers (continued):
Sharing a sentence is not in itself a finding about the gene and the disease.
Stroke (8 papers, 2012 to 2024). Sudden impairment of blood flow to a part of the brain due to occlusion or rupture of an artery to the brain. "Recent findings suggest an association between uromodulin and left atrial remodeling, as well as left atrium size, with implications for conditions like atrial fibrillation, stroke, heart failure, and increased cardiovascular disease rates and mortality." (PMID 39049957, 2024). "We next investigated the role of blood pressure in pregnancy-associated uromodulin changes by treating pregnant Stroke–Prone Spontaneously Hypertensive rats with antihypertensives nifedipine (a calcium channel blocker) or propranolol (a beta-blocker)." (PMID 38236469, 2024). "Utilizing the Blood and Clot Thrombectomy Registry and Collaboration (BACTRAC) (clinicaltrials.govNCT03153683), a continuously enrolling tissue bank, we aimed to examine the associations between serum uromodulin, age, and high BMI (BMI>25) and its relationship to stroke in patients." (PMID 33768217, 2021). "However, there was a pregnancy-associated increased expression of uromodulin protein in total kidney extract in pregnant Stroke-Prone Spontaneously Hypertensive rats (FC: 1.5, p < 0.0001) and pregnant Wistar Kyoto rats (FC: 1.3, p = 0.005) compared to non-pregnant animals." (PMID 38236469, 2024). "Stroke–Prone Spontaneously Hypertensive rats had lower uromodulin excretion pre-pregnancy that gradually increased across gestation compared to normotensive Wistar Kyoto rats." (PMID 38236469, 2024). "As a result, we chose Stroke-Prone Spontaneously Hypertensive rats as the chronic hypertensive rodent model to further investigate the role of uromodulin in renal adaptation in pregnancy." (PMID 38236469, 2024). "To further explore renal pathophysiology, we investigated uromodulin excretion and expression changes during pregnancy in a rodent model of chronic hypertension, i.e., the Stroke–Prone Spontaneously Hypertensive rat." (PMID 38236469, 2024). "An AKI can decrease kidney function which can include a decrease in uromodulin production, explaining the decreased levels of uromodulin expression in those that experienced a stroke." (PMID 33768217, 2021). "The pregnant stroke-prone spontaneously hypertensive rat shows elevated levels of polymerization-competent uromodulin, which is significantly reduced with antihypertensive treatment." (PMID 28348009, 2017). "We identified elevated levels of uromodulin peptides in the urine of pregnant stroke-prone spontaneously hypertensive rat relative to the control Wistar–Kyoto rat." (PMID 28348009, 2017). "Utilizing the proteomic data base from BACTRAC, we aimed to analyze uromodulin in the setting of large vessel occlusion stroke to understand the relationship between its intravascular levels and specific elements of stroke such as age, high BMI (BMI>25), and other comorbidities." (PMID 33768217, 2021). "There are recent reports that uromodulin may have a role in blood pressure regulation and uric acid metabolism, both of which link with outcome after stroke." (PMID 22615742, 2012). "In this model, we observed that the pre-pregnancy uromodulin excretion rates in chronic hypertensive rats (Stroke–Prone Spontaneously Hypertensive rats) are lower than in normotensive rats (Wistar Kyoto rats)." (PMID 38236469, 2024). "Both nifedipine and propranolol treatment did not significantly influence the excretion of urinary uromodulin compared to pregnant Stroke-Prone Spontaneously Hypertensive rats." (PMID 38236469, 2024). "Nifedipine- and propranolol-treated pregnant Stroke–Prone Spontaneously Hypertensive rats showed no change in kidney uromodulin mRNA expression compared to placebo control pregnant Stroke–Prone Spontaneously Hypertensive rats." (PMID 38236469, 2024). "Elevated levels of polymerization-incompetent uromodulin were seen in pregnant stroke-prone spontaneously hypertensive rat, which were not detectable in nifedipine-treated pregnant stroke-prone spontaneously hypertensive rat." (PMID 28348009, 2017).
Stroke (continued). "Whilst we were unable to assess polymerization status of uromodulin in this study, we have previously shown that nonpolymerizing uromodulin is increased in the urine of pregnant Stroke-Prone Spontaneously Hypertensive rats compared to pregnant Wistar Kyoto rats." (PMID 38236469, 2024).
heart failure (7 papers, 2018 to 2024). Inability of the heart to pump blood at an adequate rate to meet tissue metabolic requirements. "In patients with HFpEF, only uromodulin was significantly associated with eGFR (P = 0.001), with a significant interaction between the heart failure subgroups (P = 0.013)." (PMID 36795286, 2024). "Patients who exhibited a decrease in eGFR while maintaining high serum uromodulin levels were more likely to be male and suffer from heart failure." (PMID 37835820, 2023). "This suggests that serum uromodulin may be involved in the enhanced tubular activation of the NKCL cotransporter, potentially contributing to heart failure." (PMID 37835820, 2023).
type 2 diabetes (7 papers, 2013 to 2025). "Specific UMOD gene variants have been linked to distal tubular dysfunction, kidney function, and macroalbuminuria in adults with type 1 and type 2 diabetes." (PMID 37835820, 2023). "In patients with type 2 diabetes, the urinary glycated uromodulin concentration was markedly higher in patients with DKD than in non-diabetic CKD patients." (PMID 37835820, 2023). "Serum uromodulin also shows promise as a specific biomarker for early-stage DKD, developing in approximately 50% of genetically predisposed patients with type 2 diabetes." (PMID 37835820, 2023). "Moreover, it showed a significant decrease in serum levels of uromodulin with DKD in both type 1 (p < 0.0001) and type 2 diabetes (p = 0.002)." (PMID 39581971, 2024). "Additionally, uromodulin levels were significantly decreased in both type 1 (SMD: -0.34; 95% CI: -0.51 to -0.17; p < 0.0001) and type 2 diabetes (SMD: -0.58; 95% CI: -0.95 to -0.22; p = 0.002)." (PMID 39581971, 2024).
Fabry disease (6 papers, 2018 to 2025). Fabry disease (FD) is a progressive, inherited, multisystemic lysosomal storage disease characterized by specific neurological, cutaneous, renal, cardiovascular, cochleo-vestibular and cerebrovascular manifestations. "In the course of Fabry disease, uromodulin excretion is also disturbed, ranging from normal to markedly decreased or even absent." (PMID 40564142, 2025). "However, a study of 15 male Fabry disease patients has shown that enzyme replacement therapy leads to the normalization of urinary uromodulin excretion." (PMID 40564142, 2025). "In a study of 15 male Fabry disease patients at various clinical stages of the disease, significant quantitative and qualitative alterations in urinary uromodulin excretion were observed, suggesting a gradual decline in urinary uromodulin output." (PMID 37835820, 2023). "The level of UMOD expression was inversely proportional to the degree of lysosomal storage; it was suggested that abnormal UMOD expression in mTAL may contribute to the impaired urine-concentrating ability in Fabry disease." (PMID 29553830, 2018). "In summary, we found that mTAL was the most severely affected tubule in our mouse model of Fabry disease with polyuria, and that TAL dysfunction—reduction in the levels of Na+-K+-ATPase, UMOD, and NKCC2—impairs the urine-concentrating ability." (PMID 29553830, 2018).
IgA nephropathy (6 papers, 2013 to 2022). "In IgA nephropathy, uromodulin was shown to be associated with interstitial fibrosis/tubular atrophy and to contribute to eGFR decline." (PMID 34568379, 2021). "Urinary uromodulin level is associated with interstitial fibrosis/tubular atrophy and contributes to eGFR decline in IgA nephropathy." (PMID 23990922, 2013). "We found that lower baseline urinary uromodulin levels (P = 0.03) and higher time-average proteinuria (P = 0.04) were risk factors for rapid eGFR decline in a follow-up subgroup of the IgA nephropathy cohort." (PMID 23990922, 2013). "Here we further found that tubular atrophy/ interstitial fibrosis to be associated with urinary uromodulin levels in IgA nephropathy." (PMID 23990922, 2013). "We examined an IgAN cohort to explore whether urinary uromodulin levels at baseline are associated with the progression of IgA nephropathy." (PMID 23990922, 2013). "In IgA nephropathy, urinary uromodulin levels were lower in patients with more tubular atrophy/ interstitial fibrosis." (PMID 31065383, 2019). "We examined an IgA nephropathy cohort to determine whether uromodulin plays a role in the progression of IgA nephropathy." (PMID 23990922, 2013).
type 1 diabetes (6 papers, 2013 to 2024). "Such a protective effect of uromodulin on future events has been shown in type 1 diabetes, where patients with higher serum uromodulin levels were less likely to develop CKD." (PMID 38500759, 2024). "Based on these findings, it appears that serum uromodulin exhibits potential as a valuable tool for risk stratification and the prediction of cardiovascular disease and DKD development in adults with type 1 diabetes." (PMID 37835820, 2023). "Children/adolescents with type 1 diabetes exhibit serum uromodulin concentrations comparable to those of healthy controls." (PMID 37835820, 2023). "Lower serum uromodulin concentrations in individuals with type 1 diabetes are likely attributable to a change in uromodulin excretion rather than a reduction in renal tubular mass." (PMID 37835820, 2023). "In addition to potentially indicating abnormalities in tubular mass, the reduced circulating uromodulin levels in adolescents with type 1 diabetes might also suggest the involvement of tubulointerstitial dysfunction in the development of kidney dysfunction." (PMID 37835820, 2023). "Consequently, factors such as serum uromodulin concentration, which influence vascular inflammation, may have significant clinical relevance in the context of type 1 diabetes." (PMID 37835820, 2023). "The reason for the decrease in serum uromodulin in patients with type 1 diabetes remains unclear." (PMID 37835820, 2023). "Over the course of 12 years, the connections between serum uromodulin, CAC progression, and the development of DKD were examined in the coronary artery calcification in Type 1 Diabetes (CACTI) study (n = 527)." (PMID 37835820, 2023).
cystic kidney disease (5 papers, 2012 to 2026). A congenital or acquired kidney disorder characterized by the presence of renal cysts. "The role of the UMOD gene in the etiology of kidney diseases is further supported by rare UMOD variants causing monogenic forms of cystic kidney disease (MIM #162000, #603860, #609886)." (PMID 22693617, 2012). "Mutations of the uromodulin-coding gene (UMOD) may cause severe kidney disease, such as cystic kidney disease, recurring urinary tract infections, familial juvenile hyperuremic nephropathy and congenital nephrolithiasis." (PMID 32764816, 2020).
medullary cystic kidney disease type 2 (5 papers, 2014 to 2020). An inherited form of cystic kidney disease leading to fibrosis and impaired renal function that is caused by mutations in the UMOD gene, which encodes uromodulin/Tamm-Horsfall mucoprotein. "Mutations in the uromodulin gene (UMOD) cause an autosomal dominant tubulo-interstitial kidney disease." (PMID 26673890, 2015). "UMOD mutation may cause either medullary cystic kidney disease type 2 (MIM 603860) or familial juvenile hyperuricemic nephropathy (MIM 162000)." (PMID 27489562, 2016). "Several uromodulin mutations have been discovered in patients with the FJHN phenotype, now categorised as FJHN type 1." (PMID 24886545, 2014).
interstitial nephritis (4 papers, 2018 to 2024). Inflammation of the renal tubules and supporting tissues of the kidney. "Notably, a similar phenotype is often observed in patients with heterozygous variants of UMOD, MUC1, and REN genes, which cause an autosomal dominant form of tubulointerstitial nephritis." (PMID 38674137, 2024).
kidney injury (4 papers, 2023 to 2025). Trauma to the kidney. "Uromodulin (UROM_HUMAN), the protein most abundantly expressed in the urine of healthy patients, decreased significantly in our patients with kidney injury, possibly due to tubular damage leading to decreased excretion into the tubular lumen that contains urine." (PMID 37873871, 2023).
acute pancreatitis (3 papers, 2017 to 2023). An acute inflammatory process that leads to necrosis of the pancreatic parenchyma. "In another clinical study in acute pancreatitis related AKI, serum uromodulin concentration had a positive correlation with GFR, and patients with AKI had lower serum uromodulin." (PMID 32974364, 2020). "While serum uromodulin correlated with kidney function in the early phase of severe acute pancreatitis, it did not reliably predict acute pancreatitis severity or AKI development." (PMID 37835820, 2023). "However, measuring serum uromodulin did not provide a reliable means to predict the development of AKI during acute pancreatitis." (PMID 37835820, 2023).
autosomal dominant polycystic kidney disease (3 papers, 2014 to 2024). Autosomal dominant form of polycystic kidney disease. "Early studies based on radioimmunoassays found reduced uromodulin excretion in patients with tubular damage or autosomal dominant polycystic kidney disease (ADPKD)." (PMID 37322316, 2024). "HNF1B is known to regulate transcription of polycystic kidney and hepatic disease (PKHD1), uromodulin (UMOD) and polycystic kidney disease 2 (PKD2)." (PMID 29576871, 2018).
Bartter syndrome (3 papers, 2019 to 2024). "Here, we investigated the functional link between ROMK and uromodulin in Kcnj1 knock-out mouse models, in primary cultures of mouse TAL (mTAL) cells, and in patients with Bartter syndrome due to KCNJ1 mutations." (PMID 31863061, 2019). "It should also be pointed that the defect in uromodulin processing might contribute to the Bartter syndrome phenotype." (PMID 31863061, 2019).
coronary artery disease (3 papers, 2011 to 2024). "Genetic and experimental findings were not in complete agreement or even had opposite results, suggesting that further studies are still needed to validate the association between uromodulin and coronary heart disease outcomes." (PMID 39049957, 2024). "This study within persons with known coronary artery disease (CAD) evaluated whether uromodulin concentrations could distinguish CKD risk." (PMID 21235779, 2011).
glomerular diseases (3 papers, 2012 to 2024). "In patients with glomerulopathies in the early stage of tubular atrophy and renal fibrosis, serum uromodulin decreased, while estimated glomerular filtration rate (eGFR) values still remain normal." (PMID 39061561, 2024). "Serum uromodulin is an early biomarker for tubular atrophy and interstitial fibrosis in patients with glomerulopathies." (PMID 36301848, 2022). "The IgA–uromodulin complex, especially compared to total urine protein, could effectively detect IgAN by differentiating it from other glomerular diseases." (PMID 22415778, 2012).
glomerulonephritis (3 papers, 2013 to 2023). A renal disorder characterized by damage in the glomeruli. "Although uromodulin interacts with various molecules and cells, such as complement factors, cytokines, IgG, T cells, neutrophils, and monocytes, the specific immunomodulatory effects of uromodulin in ANCA-associated glomerulonephritis remain unclear." (PMID 37835820, 2023).
lupus nephritis (3 papers, 2012 to 2024). Glomerulonephritis in the context of systemic lupus erythematosus. "Studies based on mass spectrometry or ELISA identified uromodulin as a potential biomarker in Fabry nephropathy, active lupus nephritis with tubulointerstitial inflammation and in ADPKD." (PMID 37322316, 2024). "S2 Table shows the utility values of serum uromodulin levels and sUromod/eGFR index in Lupus nephritis and SLE patients (renal SLEDAI ≥ 4)." (PMID 36301848, 2022). "However, none of them had evaluated whether a low serum uromodulin adjusted by the glomerular filtration rate (sUromod/eGFR index) contributed to identify patients in risk of lupus nephritis (LN) using multivariable models." (PMID 36301848, 2022).
polycystic kidney disease (3 papers, 2013 to 2023). A usually autosomal dominant and less frequently autosomal recessive genetic disorder characterized by the presence of numerous cysts in the kidneys leading to end-stage renal failure. "Three genes in EDS patients affect the kidney: the sodium chloride co-transporter SLC12A3 associated with Gitelman syndrome M263800, uromodulin UMOD associated with renal tubular disease M263800, and PKD1 associated with polycystic kidney disease M173100." (PMID 37504295, 2023).
Polyuria (3 papers, 2018 to 2023). An increased rate of urine production. "We found that the down-regulation of 3 core molecules for Na+ reabsorption—Na+-K+-ATPase, UMOD, and NKCC2—contributed to the development of polyuria in GlatmTg(CAG-A4GALT) mice via impairment of TAL." (PMID 29553830, 2018).
cyst (2 papers, 2017 to 2021). A sac-like closed membranous structure that may be empty or contain fluid or amorphous material. "Increased excretion of collagen fragments is consistent with the active extracellular matrix (ECM) remodeling that has been related to ECM modifications observed during cyst expansion, while reduced urine uromodulin excretion has been associated with diminished markers of renal tubular function." (PMID 33737325, 2021). "Indeed, different members of the same family may have variable cyst formation; this variation may be due to other genetic differences or environmental factors rather than to different UMOD mutations." (PMID 28325753, 2017).
Dent disease (2 papers, 2021 to 2024). Dent disease is a rare genetic renal tubular disease characterized by manifestations of proximal tubule dysfunction. "UMOD, CLCN5, OCRL, NPHP4, and TTC21B may cause tubulointerstitial diseases such as ADTKD, NPHP, or Dent disease, but they are now included in the genetic panels for genetic screening of patients affected by FSGS, as they can phenocopy it." (PMID 37728640, 2024).
kidney cancer (2 papers, 2010 to 2014). Primary or metastatic malignant neoplasm involving the kidney. "The best three single gene discriminators are found to be UMOD, ACPP and CCL18 for kidney cancer, having the same classification accuracy, 98.6% on the training set and 100% and 94.4%, 95.7% and 86.11% and 89.4% and 68.1% on the two test sets, respectively." (PMID 21060876, 2010). "In particular, two ions at m/z 1670 and 2216 observed in MALDI-LM spectra were identified as fragments of the human glycoprotein uromodulin (UMOD/THP) and they were present in higher concentration in patients affected by both ccRCC and other malignant kidney tumours." (PMID 25202906, 2014).
kidney inflammation (2 papers, 2022 to 2024). "Analysis of AKI204 at the single-peptide level suggested divergences of AKI mechanisms between sexes due to increased kidney inflammation in women (increased abundance of urinary fragments of osteopontin and uromodulin)." (PMID 38699482, 2024). "Only two previous studies in systemic lupus erythematosus (SLE) patients have identified that the blood concentrations of uromodulin are lower in nephritis." (PMID 36301848, 2022).
lupus (2 papers, 2022 to 2023). "In the MRL-lpr/lpr mouse model, which mimics lupus tubulointerstitial nephritis and lupus glomerulonephritis seen in humans with SLE, two immune process-related molecules (uromodulin and β2-microglobulin) were identified in both urine and kidney tissues." (PMID 37835820, 2023). "In a cross-sectional study of 114 SLE patients, low serum uromodulin levels and a low serum uromodulin/eGFR index were correlated with higher scores of renal systemic lupus erythematosus disease activity index (SLEDAI), systemic lupus collaborating clinics (SLICC), kidney function, and proteinuria." (PMID 37835820, 2023).